TNF (tumor necrosis factor)
Diseases named in the same sentence as TNF in open-access papers (continued):
Sharing a sentence is not in itself a finding about the gene and the disease.
rheumatoid arthritis (continued). "The primary comorbidity associated with cryptococcosis is HIV coinfection; however, recent use of anti-tumor necrosis factor alpha (TNF-α) monoclonal antibodies in the context of rheumatoid arthritis is associated with an increased risk of cryptococcosis." (PMID 33568457, 2021). "Calcium-dependent NFAT activation caused IL-17 and TNF-α secretion associated with autoimmune disease rheumatoid arthritis." (PMID 35126366, 2021). "Grape polyphenols have shown immuno-regulatory effects, establishing a balance between Th17 and Treg cells and inhibiting TNFα in rheumatoid arthritis, hence mitigating inflammation, oxidative stress and rheumatoid arthritis associated symptoms." (PMID 33668814, 2021). "The present meta-analysis was carried out to assess the risk of infection and other side effects after anti-TNF- α for the treatment of rheumatoid arthritis, psoriatic arthritis, and ankylosing spondylitis." (PMID 34790122, 2021). "IL-6 and TNF-α are proinflammatory cytokines whose elevations have been associated with pathologies of rheumatoid arthritis." (PMID 34108880, 2021). "TNF-α has been linked with pathological conditions, such as rheumatoid arthritis, atherosclerosis, psoriasis, Crohn’s disease, and sepsis." (PMID 33435569, 2021). "Toll-like receptor (TLR)-4 and TLR9 are known to play important roles in the immune system, and several studies have shown their association with the development of rheumatoid arthritis (RA) and regulation of tumor necrosis factor alpha (TNF-α)." (PMID 34635730, 2021). "TNF-α and IL-1β are the highly substantial inflammatory mediators reported in association with several inflammatory diseases including rheumatoid arthritis, bacterial sepsis, skin inflammation and many others." (PMID 33933037, 2021). "TNF-α inhibitor use in elderly patients with rheumatoid arthritis has shown lower efficacy and increased risk of tuberculosis reactivation, serious infections, and skin cancer." (PMID 34732807, 2021). "The FCGR3A-158FF variant was associated with better response to anti-TNF medication at 6 weeks of treatment in a study with 35 American patients diagnosed with psoriatic pathology (n = 5) and rheumatoid arthritis (n = 30) (47.8% vs. 0%; p < 0.01)." (PMID 33921427, 2021). "We focused on AD risk among people with rheumatoid arthritis, psoriatic arthritis, ankylosing spondylitis, Crohn’s disease, ulcerative colitis, and related conditions, where TNF-a is implicated, and TNF-a inhibiting drugs are FDA approved for use." (PMID 34763722, 2021). "Indirect evidence has also shown that single-nucleotide genetic polymorphisms in the 5-HT2A receptor gene are associated with rheumatoid arthritis, a disease that is linked to increased TNF-α levels, and are responsive to TNF-α antagonists." (PMID 34959614, 2021). "Clinically available inhibitors of IL-1 and TNF-α reduce the sleepiness and fatigue associated with rheumatoid arthritis and sleep apnea." (PMID 34943452, 2021). "In the 2000s, anti-tumor necrosis factor therapy for rheumatoid arthritis was linked to an increased risk for infection and malignancy." (PMID 34235145, 2021). "TNF-α is associated with systemic inflammation in rheumatoid arthritis, ankylosing spondylitis, and periodontitis." (PMID 33861790, 2021). "In a clinical setting, TNF-α inhibitors are widely used to treat TNF-α-associated disorders, including rheumatoid arthritis, psoriasis, ankylosing spondylitis, Crohn’s disease, diabetes mellitus, Alzheimer’s disease, and cancer." (PMID 34357066, 2021). "A study using high doses of vitamin D3 (more than 60,000 IU) reported the resolution of anti-TNFα-induced psoriasiform lesions in a patient with rheumatoid arthritis and vitamin D deficiency." (PMID 33419149, 2021). "It was recently reported that in patients with autoimmune diseases such as rheumatoid arthritis, treatment with tumor necrosis factor (TNF) inhibitor increased the risk of CNS inflammation and subsequent BBB breakdown." (PMID 33381913, 2021).
rheumatoid arthritis (continued). "In fibroblast like synoviocytes (FLS), which are implicated in the inflammation in rheumatoid arthritis, TNF-alpha-mediated induction of IRF1 leads to induction of inflammatory mediators, such as IFN-gamma." (PMID 34211464, 2021). "TNFα-mediated inflammatory pathways have been strongly implicated in several diseases, including atherosclerosis, rheumatoid arthritis, psoriasis, type II diabetes, depression, schizophrenia, and AD." (PMID 32973771, 2020). "Further, synovial fibroblasts from patients with rheumatoid arthritis were shown to release EVs that express membrane-associated TNF that reduces the activation-induced cell death of CD4+ T cells." (PMID 32547552, 2020). "In the rheumatoid arthritis subgroup (n = 96), exposure to TNF inhibitors was associated with greater risk of developing any inflammatory demyelinating or nondemyelinating CNS events (adjusted OR, 4.82; 95% CI, 1.62-14.36; P = .005)." (PMID 32421186, 2020). "We separately assessed the effects of gender, age, and race on the effect of TNF blocking agents on the risk of dementia among patients with rheumatoid arthritis." (PMID 32203525, 2020). "Deficiency of iRhom2 not only attenuates TNFα production by leukocytes but also reduces several leukocyte driven immune responses including bacterial sepsis and rheumatoid arthritis." (PMID 32825187, 2020). "TNF-α accelerates other pro-inflammatory cytokines and gene expression, inducing the risk of rheumatoid arthritis, asthma and inflammatory bowel disease." (PMID 32942640, 2020). "In the article titled “The Association of TNF-Alpha Inhibitors and Development of IgA Nephropathy in Patients with Rheumatoid Arthritis and Diabetes”, Dr. Mario Laganović, Dr. Tajana Željković-Vrkić, and Dr. Jelena Kos were missing from the authors' list." (PMID 32953188, 2020). "Deregulation of the TNF-α signaling pathway is associated with many inflammatory disorders, including rheumatoid arthritis, and inflammatory bowel disease, as the monoclonal antibody to TNF-α has been a standard treatment for these diseases." (PMID 33322487, 2020). "The suppression of PRR5L expression has been suggested to promote tumor necrosis factor alpha (TNFα)-associated autoimmune diseases, such as asthma, rheumatoid arthritis, psoriasis, and inflammatory bowel disease at adulthood." (PMID 33096704, 2020). "The KEGG pathway analysis revealed that these genes were mainly associated with the TNF signaling pathway, cytokine-cytokine receptor interaction, rheumatoid arthritis, and chemokine signaling pathway." (PMID 33144895, 2020). "5-HT modulation can alleviate various TNFα-mediated inflammatory diseases, including depressive disorders linked to systemic inflammation, GI disorders, atherosclerosis, rheumatoid arthritis, psoriasis, type II diabetes, schizophrenia, and AD." (PMID 32973771, 2020). "In the secondary analyses stratified by autoimmune disease, the association of inflammatory CNS events with TNF inhibitor exposure was observed in patients with rheumatoid arthritis." (PMID 32421186, 2020). "Pro-inflammatory cytokines including IL-6, IL-1β, and TNF-α are secreted from macrophages after LPS treatment, and they are linked to various chronic diseases, including rheumatoid arthritis, type II diabetes, and cancer." (PMID 32238770, 2020). "TNF-α causes inflammatory reactions in the body, which leads to such serious diseases as rheumatoid arthritis, ankylosing spondylitis, Crohn’s disease, psoriasis, refractory asthma and others." (PMID 33212930, 2020). "Low dose prednisone (10 mg/day) is used to treat rheumatoid arthritis, presumably by suppressing immune activation and TNF production, but long-term use is associated with increasingly unacceptable side effects." (PMID 32203525, 2020). "The recommendation of tuberculosis screening was originally based on anti-TNF-α agents risk management plan during treatment of rheumatoid arthritis." (PMID 31881026, 2019).
rheumatoid arthritis (continued). "In rheumatoid arthritis (RA) patients, both disease-related and iatrogenic immune dysfunction affect the risk of cryptococcosis, especially corticosteroid and TNFα inhibitor use." (PMID 31382367, 2019). "The KEGG annotation showed that the top 5 enriched pathways of these DEGs are immune-associated, namely, the TNF-signaling pathway, IL-17 signaling pathway, rheumatoid arthritis, NF-κB signaling pathway, and NOD-like receptor signaling pathway." (PMID 31737164, 2019). "Tumor necrosis factor-α (TNF-α), mainly produced in macrophages through LPS-mediated NF-κB activation, is associated with various inflammatory conditions such as sepsis, rheumatoid arthritis, inflammatory bowel disease, and so on." (PMID 31083310, 2019). "Reduction of macrophage populations at the synovial level has previously been observed in rheumatoid arthritis patients treated with TNF-α blockers and has been associated with increased macrophage-specific apoptosis as compared with untreated patients." (PMID 31475008, 2019). "This module consisted of 18 nodes and 144 edges, which are mainly associated with inflammatory response, immune response, TNF signaling pathway, and rheumatoid arthritis, etc.." (PMID 31921295, 2019). "The inflammatory biomarker TNFα‐308G>A has been associated with increased severity of rheumatoid arthritis: erosion and significant joint damage (Lee, Ji, & Song, 2007)." (PMID 31566926, 2019). "On the other hand, dysregulation of TNF has been linked to the development of inflammatory diseases including rheumatoid arthritis (RA), inflammatory bowel diseases (IBD) and psoriasis." (PMID 31457011, 2019). "Multiple proinflammatory cytokines, such as IL-1β, IL-6, TNF-α, and IL-17, cause cartilage damage and bone destruction in aggravation of rheumatoid arthritis." (PMID 29751535, 2018). "In patients with rheumatoid arthritis, who are at risk of cardiovascular disease, anti–TNF-α treatment has been shown to be protective but also, in some cases, to increase the risk of MI." (PMID 29415889, 2018). "Patients with rheumatoid arthritis receiving anti-TNF immunotherapy have the increased risk of fungal and bacterial infections, particularly of reactivating latent tuberculosis, as well as non-melanoma skin cancers." (PMID 29636466, 2018). "This case report describes a patient with highly suspected primary intraocular lymphoma (PIOL), possibly associated with use of the approved anti-TNFα agent etanercept for treatment of rheumatoid arthritis (RA)." (PMID 29954352, 2018). "In rheumatoid arthritis, IL-6 has the function of increasing the effect and secretion of IL-1 and TNF-α and is also the main marker that is associated with disease activity." (PMID 29805310, 2018). "With respect to cardiac development, LTB is identified as a risk factor altered for cardiovascular diseases and thus the TNF antagonist potentially acts as a likely candidate to reduce the CVD risk in rheumatoid arthritis patients." (PMID 29026152, 2017). "This study evaluated the effect of early anti-tumor necrosis factor (TNF) therapy in patients with severe rheumatoid arthritis (RA) on the subsequent risk of total knee replacement (TKR) surgery." (PMID 28764690, 2017). "S1P and SPHK1 are associated with the actions of TNF-α, a cytokine critical for inflammation and autoimmune disorders, for example, inflammatory bowel disease, rheumatoid arthritis, and asthma." (PMID 28270699, 2017). "Rheumatoid arthritis (RA) is a systemic inflammatory disease associated with increased levels of inflammatory mediators, including tumour necrosis factor α (TNF-α) and T helper (Th) 17 cells, and downregulation of apoptosis of inflammatory cells." (PMID 28860618, 2017). "Dysregulation of TNF signaling has been associated with anorexia and cachexia in a number of medical illnesses including rheumatoid arthritis, inflammatory bowel disease, and malignancies." (PMID 28846695, 2017).
rheumatoid arthritis (continued). "Tumor Necrosis Factor alpha (TNFα) is a homotrimeric cytokine of the immune system whose overproduction has been associated with several chronic inflammatory diseases such as rheumatoid arthritis, Crohn’s disease or psoriasis." (PMID 28611375, 2017). "Tumor necrosis factor-alpha (TNF-α) can cause diverse T cell dysfunctions in patients with rheumatoid arthritis (RA)." (PMID 29191214, 2017). "Large cohort studies in patients with rheumatoid arthritis and psoriasis showed that TNF inhibition is associated with a reduction in T2D rates." (PMID 29163354, 2017). "Rheumatoid arthritis specific autoantibody had been showed having a pathogenic role and increased TNF-α synthesis from macrophage in dose dependent manner." (PMID 28837666, 2017). "TNF-α has been reported to trigger the downstream activation of inflammatory gene expression, and to cause rheumatoid arthritis, inflammatory bowel disease, psoriasis, and refractory asthma." (PMID 28930149, 2017). "TNFα is involved in systemic inflammation and its expression is also associated with pathologies, such as rheumatoid arthritis." (PMID 28542363, 2017). "The cytokines in question, TNF-alpha and IL-6, are strongly implicated in etiology of diseases such as rheumatoid arthritis." (PMID 28946707, 2017). "TNF-α inhibitors are applied in underlying diseases such as rheumatoid arthritis, psoriasis, Crohn’s disease, and polyarteritis nodosa." (PMID 28179019, 2017). "In bone tissues, IL‐1 is a typical bone‐resorbing cytokine associated with inflammation, but other cytokines such as TNF‐α, IL‐6, and IL‐17 are known to be involved in bone destruction associated with rheumatoid arthritis." (PMID 28781957, 2017). "CSF2 is a pro-inflammatory cytokine implicated in many diseases, including diabetes, rheumatoid arthritis and cancer, through its links to other pro-inflammatory cytokine such as tumor necrosis factor (TNF) and IL-1." (PMID 29206834, 2017). "The finding that Atsttrin protected against TNFα-induced cartilage loss in multiple rheumatoid arthritis mouse models promoted us to determine the interplay between TNFα and Atsttrin in OA." (PMID 29258611, 2017). "The present study broadens our knowledge of the mechanisms underlying the immunomodulatory effects of TNF-α inhibitors in rheumatoid arthritis treatment." (PMID 27926504, 2017). "TNFα has a causative role in the pathogenesis of chronic auto-inflammatory diseases such as rheumatoid arthritis (RA) and inflammatory bowel disease (IBD)." (PMID 27982031, 2016). "Inactivation of TNFα has proven to be important in downregulating the inflammatory and immune reactions associated with rheumatoid arthritis and other autoimmune conditions." (PMID 27965661, 2016). "In the same year, another study evaluated the association between anti-TNF-αtherapy in rheumatoid arthritis and cardiovascular events, getting differentrelative risks (RR) among cohort studies and randomized controlled trials." (PMID 28099601, 2016). "TNF has been associated with rheumatoid arthritis (RA), psoriasis, psoriatic arthritis, and ankylosing spondylitis." (PMID 27382576, 2016). "In rheumatoid arthritis, the use of anti-TNF was associated with reducedrisk of cardiovascular events (RR 0.7, 95% CI 0.54 to 0.9; p<0.005), acutemyocardial infarction (AMI), stroke and MACE." (PMID 28099601, 2016). "TNF-alpha expression is critically linked to host protection, since latently M. tuberculosis-infected individuals that received anti-TNF reagents to treat inflammatory diseases (e.g., rheumatoid arthritis) showed an enhanced TB reactivation risk." (PMID 28082976, 2016). "The protectivity of TNF-α is supported by the fact that chemical blockers of TNF-α used for treating rheumatoid arthritis have caused the reactivation of tuberculosis." (PMID 28066410, 2016).
rheumatoid arthritis (continued). "During inflammation, excess levels of cytokines (IL-1β, IL-6, and TNF-α) lead to the damaging of cells and tissues and the activation of macrophages in inflammation-associated diseases (e.g., rheumatoid arthritis and chronic hepatitis)." (PMID 27493450, 2016). "Hyperactivity of the TNF pathway has been associated with several chronic autoimmune and inflammatory diseases, such as psoriasis, rheumatoid arthritis, and multiple sclerosis." (PMID 27685623, 2016). "Tumor necrosis factor alpha (TNFα) has a particularly important role in the cascade of pathogenic events in rheumatoid arthritis." (PMID 26977076, 2016). "To address the question, if Thbs4-deficiency would affect the severity of joint destruction in a mouse model of rheumatoid arthritis, we additionally crossed Thbs4-deficient mice with mice carrying a transgene causing over-expression of human TNFα." (PMID 26629997, 2015). "We additionally crossed the Thbs4-deficiency into a TNF-transgenic background, which is commonly used to study the impact of specific molecules on the severity of rheumatoid arthritis." (PMID 26629997, 2015). "Polymorphisms within the TNF promoter region have been identified to influence clinical efficacy of etanercept in a study that combined patients with rheumatoid arthritis (RA), ankylosing spondylitis and PsA." (PMID 25980667, 2015). "IL-6 and TNF-α are also involved in pathogenesis of bone resorption in acute abdominal disease, rheumatoid arthritis and menopause-associated osteoporosis." (PMID 26199898, 2015). "TNF antagonists were convincingly demonstrated to reduce the risk of cardiovascular events both in rheumatoid arthritis and in psoriasis." (PMID 26633680, 2015). "TNF-α is a proinflammatory cytokine that contributes to bone loss in conditions such asinflammatory osteolysis, periodontal inflammation, rheumatoid arthritis, andpostmenopausal osteoporosis." (PMID 25923459, 2015). "It is well known, TNF blockers pose an increased risk of TB infection in adults with rheumatoid arthritis." (PMID 26047099, 2015). "The study provides new evidence supporting the critical role of TNFα in the pathogenic Th17 cell differentiation in rheumatoid arthritis." (PMID 25436214, 2014). "In a prospective study assessing the risk of herpes zoster in more than 5000 patients with rheumatoid arthritis treated with anti-TNF drugs, 86 episodes of herpes zoster were recorded in 82 patients; in two of these patients PHN occurred." (PMID 25127283, 2014). "Increased production of TNFα is associated with the development of autoimmune/chronic inflammatory diseases, including psoriasis, lichen planus, rheumatoid arthritis, and IBD." (PMID 24802997, 2014). "Despite of the good efficacy of biologic agents such as TNF-α or IL-1β blocker for many patients with rheumatoid arthritis, augmented risk of some adverse side effects such as infection and malignancy still persist in concern." (PMID 25229347, 2014). "TNFα overexpression has been associated with several chronic inflammatory diseases, including psoriasis, lichen planus, rheumatoid arthritis, and inflammatory bowel disease." (PMID 24802997, 2014). "Overproduction of TNF-α by macrophages has been also linked to several inflammatory diseases including cancer, sepsis, rheumatoid arthritis, and inflammatory bowel disease." (PMID 25329163, 2014). "Competitive elution of phages was obtained using the monoclonal antibody adalimumab, which neutralizes pro-inflammatory processes caused by over-production of TNF-α in vivo, and is used to treat severe symptoms of rheumatoid arthritis." (PMID 24896264, 2014). "Enhanced TNFα synthesis is associated with the development of autoimmune/chronic inflammatory diseases, including psoriasis, lichen planus, rheumatoid arthritis, and inflammatory bowel disease (IBD)." (PMID 24802997, 2014).